IL22 (interleukin 22)
Diseases named in the same sentence as IL22 in open-access papers (continued):
Sharing a sentence is not in itself a finding about the gene and the disease.
periodontal disease (5 papers, 2022 to 2025). "Th17 cells, which originate from CD4+ T cells, have been shown to play a pivotal role in the progression and regulation of periodontal disease, with the cytokines they secrete (mainly IL-17 and IL-22) being a key factor in this process." (PMID 40076898, 2025). "NGAL expression can be stimulated by many cytokines and growth factors that may contribute to periodontal diseases, such as interleukin-1, IL-17, IL-22, insulin-like growth factor-1, transforming growth factor alpha, and tumor necrosis factor-alpha." (PMID 41040472, 2025). "In addition, similar levels of IL-22 gene expression were observed in healthy and peri-implantitis patients, which shows a pattern contrary to what has been described for periodontal disease studying the Th22 T cells subpopulation." (PMID 35742682, 2022). "In relation to IL-22, there is little evidence of its role in the pathogenesis of periodontal disease, however, it is known to play an important role in mucosal immunity." (PMID 38431633, 2024).
peritonitis (5 papers, 2014 to 2025). Inflammation of the peritoneum (tissue that lines the abdominal wall and covers most of the organs in the abdomen). "The significance of IL-10 and IL-22 upon AhR activation for preventing septic course of S.E.-induced peritonitis has to be elucidated in further studies." (PMID 35203386, 2022). "Administration of an anti-IL22 blocking antibody results in higher bacterial loads in the lungs and dissemination of bacteria to spleen, whereas therapeutic administration of IL22 attenuates Klebsiella-triggered peritonitis." (PMID 30452654, 2019). "However, the adverse effects of IL-22 are also described in a model of polymicrobial peritonitis, in which the levels of IL-22 and its receptor in the spleen and kidney were very high." (PMID 25614712, 2014).
stable angina (5 papers, 2019 to 2024). "They reported significantly higher plasma IL-22 levels in NSTEMI patients (33.09 ± 6.53 pg/mL) than in the patients with unstable angina (29.86 ± 3.49 pg/mL, p = 0.02), patients with stable angina (26.96 ± 3.09 pg/mL, p < 0.001), and healthy controls (24.16 ± 2.46 pg/mL, p < 0.001)." (PMID 39274184, 2024).
Stroke (5 papers, 2016 to 2026). Sudden impairment of blood flow to a part of the brain due to occlusion or rupture of an artery to the brain. "The research about the role of γδ T cell-derived IL-22 in brain ischemic stroke is rare, and the neuroprotective effect of IL-22 in stroke needs more evidence to verify." (PMID 35432162, 2022). "In this study, we demonstrated that patients with low stroke risk have increased mRNA expression of GATA-3, Foxp3, PU.1, AHR, IL-9, IL-22 and IL-10." (PMID 27115869, 2016). "We observed that low stroke risk patients exhibited higher GATA-3, Foxp3, PU.1, AHR, IL-9, IL-10 and IL-22 expression levels than did patients with high stroke risk." (PMID 27115869, 2016). "Peripheral blood of stroke patients showed significantly elevated levels of DNAse-I (p < 0.001), LDG (p = 0.003), CD4 (p = 0.005) as well as the pro-inflammatory cytokines IL-17 (p < 0.001), INF-γ (p < 0.001) and IL-22 (p < 0.001) compared to controls, reflecting a TH1/TH17 response." (PMID 35596126, 2022).
synovitis (5 papers, 2013 to 2024). Inflammation of a synovial membrane. "This suggests that IL-22-facilitated osteoblast differentiation is more prominent in RA-related joint destruction resulting from synovitis as compared with that observed during normal bone metabolism." (PMID 30619268, 2018). "Synovitis in RA is characterized by the continuous influx of immune cells and the production of various pro-inflammatory cytokines such as TNF, IL-1, IL-17, and IL-22, which stimulate bone and cartilage inflammation and damage." (PMID 39104791, 2024).
visceral leishmaniasis (5 papers, 2015 to 2018). A severe form of leishmaniasis characterized by irregular bouts of fever, substantial weight loss, swelling of the spleen and liver, and anemia (which may be serious). "In visceral leishmaniasis, it was shown that L. donovani promote IL-17 and IL-22 production by T CD4+ cells from healthy volunteers and patients." (PMID 29867796, 2018). "Along with signature Th1 cytokines, IL-17 and IL-22 were also found to have complementary roles in protection against visceral leishmaniasis and it was postulated that defects in the Th17 induction could increase the risk of visceral leishmaniasis." (PMID 27175732, 2016). "Along with signature Th1 cytokines, IL-17 and IL-22 were found to have complementary roles in protection against kala-azar as it was postulated that a defect in Th17 induction could increase the risk of kala-azar." (PMID 26465878, 2015). "Since stromal cells play a role in immunoregulation in visceral leishmaniasis, one possibility is that stimulation of stromal cells by IL-22 might indirectly influence the development of disease." (PMID 26285207, 2015). "However, this is in contrast to visceral leishmaniasis, where the production of IL-22 has been correlated with increased protection." (PMID 26285207, 2015). "How IL-22 promotes resistance in visceral leishmaniasis is unknown, but it is unlikely to be a direct effect on the parasites, since the IL-22R is not expressed on the cells infected with leishmania." (PMID 26285207, 2015).
abortion (4 papers, 2016 to 2023). the ending of pregnancy by removing a fetus or embryo before it can survive outside the uterus. "The lower number of stromal cells can be due to stromal edema that occurred in IL-22-deficient mice post endotoxin-induced abortion." (PMID 36091010, 2022). "According to our results, uterine tissues from IL-22-deficient mice that experienced LPS-triggered abortion have significantly lower levels of an antimicrobial protein called mucin-1 than tissues from WT mice." (PMID 36091010, 2022). "This work demonstrates that IL-22 is key for the proper regeneration of endometrial layers after inflammation-triggered abortion." (PMID 36091010, 2022). "Among eleven IL-22−/− mice, there was one mouse that managed to become pregnant following recovery after LPS-induced abortion." (PMID 36091010, 2022). "Our data suggest that IL-22 plays an important role in controlling the excessive production of ECM in uterine regenerative process after abortion." (PMID 36091010, 2022). "We evaluated the expression of claudin-2, claudin-3, and claudin-10 in the uterine samples from IL-22−/− and WT mice after LPS-triggered abortion." (PMID 36091010, 2022). "A considerable difference was observed between IL-22−/− and WT mice in the uterine clearance following LPS-triggered abortion." (PMID 36091010, 2022). "In our current study, we hypothesized that IL-22 is involved in the regeneration of uterine mucosal tissue after inflammation-triggered abortion." (PMID 36091010, 2022). "Therefore, IL-22 contributes to the proper regeneration of endometrial layers after inflammation-triggered abortion." (PMID 36091010, 2022). "Here, we studied the role of IL-22 in endometrial recovery after inflammation-triggered abortion." (PMID 36091010, 2022). "Knowing that IL-22 participates in tissue repair after an injury, we hypothesized that the absence of IL-22 might hinder endometrial regeneration after LPS-triggered abortion in IL-22−/− mice and affect the mice’s ability to become pregnant in subsequent matings." (PMID 36091010, 2022). "In those experiencing successful pregnancy and those experiencing unexplained recurrent abortion (URA), the levels of IL-22 produced by decidual CD4+ T cells are higher than those of peripheral blood T cells." (PMID 30669479, 2019). "However, the percentages of Th2 (p = 0.00001) and Th17/Th2 (producing IL-4 plus IL-17A, IL-17F and IL-22) (p = 0.001) T cell clones were significantly higher in the decidua of normal pregnancy compared to decidua of women suffering from unexplained recurrent abortion." (PMID 26798325, 2016). "The regulation of proteolytic enzymes in endometrial repair after LPS-induced abortion is IL-22 independent, as the difference between the groups was not significant." (PMID 36091010, 2022). "Therefore, we can conclude that IL-22 is not essential in the recruitment of matrix metalloproteinase to repair the endometrium after LPS-induced abortion." (PMID 36091010, 2022).
acne (4 papers, 2014 to 2024). An inflammatory process of the sebaceous glands which is characterized by comedones, nodules, papules and/or pustules on the skin. "Th17 lymphocytes are also involved in the pathogenesis of acne, presenting as increased expression of IL-17 and IL-22 in peripheral blood mononuclear cells induced by P. acnes; IL-17 was detected in the biopsy of AL." (PMID 31281837, 2019). "We and others reported elevated levels of IL-22 in acne lesions, suggesting that IL-22 can cooperate with IL-17 to activate epithelial cells to produce antimicrobial peptides, but more research is needed to fully understand the role of IL-22 in acne pathogenesis." (PMID 38396697, 2024). "ILC3s may play a similar role to Th17 cells in enhancing IL-17 production to promote neutrophil recruitment and inflammatory responses or enhancing IL-22 production to promote keratinocyte and fibroblast proliferation within the inflamed acne microenvironment." (PMID 38396697, 2024). "In our study elevated levels of IL-22 and IL-20 were found in acne lesions by RT-PCR." (PMID 25153527, 2014). "While the role of Th17-derived IL-17 and IL-22 responses have been studied in acne, the role of ILC3-derived IL-17 and IL-22 have yet to be elucidated." (PMID 38396697, 2024). "Furthermore, Th17 cell products IL-17A, IL-22, IL-26, TNF and IL-17 induced chemokines CSF2 and CCL20 were also expressed at higher levels in acne lesions." (PMID 25153527, 2014). "The expression of cytokines IL-6, IL-12p40, INF-γ and TGF-β have not been studied earlier in acne lesions as also noticed by Thiboutot and co-workers, nor cytokines IL-17A, IL-17F, IL-23p19, IL-22 and chemokines CCL20 and CSF2." (PMID 25153527, 2014).
acute coronary syndrome (4 papers, 2013 to 2020). Signs and symptoms related to acute ischemia of the myocardium secondary to coronary artery disease. "Another study revealed a significant increase in the number of peripheral Th22 cells and the protein levels of IL-22 and IL-9 in patients with acute coronary syndromes compared with those in the stable angina pectoris and control groups." (PMID 31011288, 2019).
acute respiratory distress syndrome (4 papers, 2020 to 2023). Progressive and life-threatening pulmonary distress in the absence of an underlying pulmonary condition, usually following major trauma or surgery. "The goal of this study was to determine if IL-22:Fc would Acute Respiratory Distress Syndrome (ARDS)." (PMID 34597299, 2021). "However, high levels of IL-22 and IL-17 were detected in plasma of patients with sepsis-induced acute respiratory distress syndrome (ARDS) and were correlated with poor prognosis." (PMID 33178223, 2020).
allergic rhinitis (4 papers, 2015 to 2021). Inflammation of the nasal mucous membranes caused by an IgE-mediated response to external allergens. "IL-22 also appears important in the defense against severe chronic rhinosinusitis, which often develops from allergic rhinitis and is associated with IL-22 receptor polymorphisms." (PMID 26565810, 2015). "IL-10, IL-17, TGF-β, IFN-γ, IL-22, and IL-35 serum levels of allergic rhinitis (AR) patients were measured using ELISA method." (PMID 29692871, 2018).
alveolitis (4 papers, 2013 to 2024). "Initial studies using a Bacillus subtilis model of hypersensitivity pneumonitis showed that IL-22 reduced inflammation and collagen deposition around the airways." (PMID 38101567, 2024). "The pathological scores of alveolitis at day 7 (p = 0.011) and fibrosis at day 21 (p = 0.007) were significantly decreased in mice treated with both BLM and IL‐22 (n = 6) as compared with BLM mice (n = 6)." (PMID 34459137, 2021).
Alzheimer disease (4 papers, 2015 to 2024). A progressive, neurodegenerative disease characterized by loss of function and death of nerve cells in several areas of the brain leading to loss of cognitive function such as memory and language. "IL-22 mRNA is highly expressed in Alzheimer’s disease (AD) patients, and a high expression of IL-22 has also been detected in the brains of patients with other NDs." (PMID 36176437, 2022). "In certain rat and APP transgenic mouse models of Alzheimer’s disease, for example, specific effector CD4+ T cells secreting IFN-γ, IL-17 or IL-22 were linked to increased neuroinflammation and exacerbation of disease progression." (PMID 26558367, 2015).
autism (4 papers, 2021 to 2025). Persistent deficits in social interaction and communication and interaction as well as a markedly restricted repertoire of activity and interest as well as repetitive patterns of behavior. "tVNS application increased brain NLRP3 levels and reduced serum IL‐1β and IL‐22 levels in the autism model." (PMID 39401991, 2025). "Childhood Autism Rating Scale (CARS) assessed ASD severity, and serum levels of IL-17 A and IL-22 were assessed by enzyme-linked immunosorbent assay (ELISA)." (PMID 38183030, 2024). "Il22 upregulation has also been reported in the BTBR mouse model of autism." (PMID 33805317, 2021). "Further extensive studies will be needed that include more advanced techniques for multiplex cytokine detection with long follow-up periods to evaluate better serum IL-17 A and IL-22 levels and functions in pediatric patients with autism and to confirm whether IL-22 correlates to ASD severity." (PMID 38183030, 2024).
autoimmune hepatitis (4 papers, 2018 to 2022). Hepatitis caused by autoantibodies. "Escin could protect against Con A-induced autoimmune hepatitis in mice via suppressing infiltration of neutrophils, CD4+ T cells, and monocytes into the liver, activation of Nrf2/HO-1 signaling pathway, inhibiting TNF-α/NF-κB, TNF-α/JNK, and IL-22/STAT3 signaling pathways." (PMID 36063304, 2022).
autoimmune uveitis (4 papers, 2013 to 2024). An autoimmune form of uveitis (disease). "For example, MAIT cells infiltrate the retina in an experimental autoimmune uveitis (EAU) model ( ~ 1.5% of T cells) where they equally seem to exert a protective function, which is at least partially mediated by IL-22 production." (PMID 39468055, 2024).
breast tumor (4 papers, 2020 to 2025). "The results of carmine staining analyses of 4‐ to 10‐week‐old mice showed a significant reduction in the growth of breast tumors during malignant transition stage in IL‐22−/−/PyMT mice." (PMID 31725949, 2020). "Mechanistically, deletion of IL‐22 gene causes downregulation of epithelial‐to‐mesenchymal transition (EMT)‐associated transcription factors in breast tumors, suggesting EMT as the mechanism of regulation of malignancy by IL‐22." (PMID 31725949, 2020). "We show that IL‐22 is highly expressed in the TME during the invasion stage of breast tumor progression and inactivation of IL‐22 gene leads to the inhibition in the malignant transition stage and reduced tumor growth." (PMID 31725949, 2020). "We found that among all the stages, IL‐22 is specifically upregulated in tumor microenvironment (TME) during the malignant transformation stage of breast tumor progression." (PMID 31725949, 2020). "In this study, we examined the changes of ILC1, ILC2, and ILC3 frequency in innate immunity, CD4+ and CD8+ T cells in adoptive immunity, and the expression of their associated cytokines (IFN-γ, IL-4, IL-10, IL-13, and IL-22) in 4T1 and MC4-L2 breast tumor models." (PMID 39877637, 2025). "Primary breast tumors were harvested from 8‐week‐old IL‐22+/+/PyMT mice." (PMID 31725949, 2020). "In addition, recIL‐22 also increased the overall breast tumor growth in IL‐22−/−/PyMT mice as demonstrated by whole‐mammary gland carmine staining." (PMID 31725949, 2020). "Using these mice, we first investigated whether inhibition of IL‐22 activity can influence the breast tumor development." (PMID 31725949, 2020).
cystic fibrosis (4 papers, 2010 to 2021). Autosomal recessive disorder caused by pathogenic variants in the CFTR gene (cystic fibrosis transmembrane conductance regulator), which encodes a chloride and bicarbonate channel expressed in epithelial cells, and follow the diagnosis criteria. "However, we identified a novel role for IL-22 in exacerbating infection-induced weight loss, an important prognostic factor in patients with cystic fibrosis, which warrants further investigation." (PMID 27375092, 2016). "In cystic fibrosis, where P. aeruginosa is a common colonizing pathogen of the lung, IL-22 is produced and is localized to the airways." (PMID 32637365, 2020). "Whether IL-22 confers protection against chronic Pseudomonas aeruginosa (PA) infection in cystic fibrosis is unknown." (PMID 27375092, 2016).
gastric MALT lymphoma (4 papers, 2014 to 2024). "In 2014, polymorphisms in Il22 were found to be associated significantly with gastric MALT lymphoma in Taiwan." (PMID 26867135, 2016). "And lastly, we recently identified five single nucleotide polymorphisms (SNPs) of IL-22 that were significantly associated with H. pylori-induced gastric MALToma (unpublished data)." (PMID 24824519, 2014). "Furthermore, in 41 gastric MALT lymphoma patients undergoing HPE, the expression of IL-22 was significantly associated with the HP-dependence of gastric MALT lymphoma." (PMID 30999581, 2019). "We previously reported that gastric tissue expression of IL-22, a Th17-related cytokine, was significantly associated with HPE responsiveness in patients with gastric MALT lymphoma." (PMID 39558403, 2024). "Gastric specimens of patients with H. pylori-induced gastric MALToma showing detectable levels of IL-22 expression tend to have undetectable levels of CCL20 expression, suggesting an inverse association of IL-22 expression and CCL20 expression in vivo." (PMID 24824519, 2014).
Glucose intolerance (4 papers, 2016 to 2026). Glucose intolerance (GI) can be defined as dysglycemia that comprises both prediabetes and diabetes. "Direct IL-22 administration elevated circulating GLP-1 and improved glucose intolerance, while GLP-1 agonist treatment rescued metabolic defects associated with reduced IL-22 signaling." (PMID 41723134, 2026). "Another study has shown that for T2DM mice, supplementing with the Bifidobacterium longum NBM7-1 and Lactiplantibacillus rhamnosus NBM17-4 alleviates glucose intolerance through the upregulation of IL-22, which enhances insulin sensitivity and pancreatic functions while reducing liver steatosis." (PMID 39062940, 2024).
insulinoma (4 papers, 2015 to 2024). "To explore the pathways downstream of IL-22ra1 signaling, we treated MIN6N8 mouse insulinoma beta-cells with IL-22 and performed RNA sequencing." (PMID 38811550, 2024). "In the present study, we demonstrated that IL-22 protected rat insulinoma cells from palmitate-induced oxidative and ER stress and that these effects were mediated by autophagy." (PMID 26784895, 2016).